MAZ (MYC associated zinc finger protein)
Diseases named in the same sentence as MAZ in open-access papers (continued):
Sharing a sentence is not in itself a finding about the gene and the disease.
cancer (continued). "circ-CUX1 knock-down inhibits aerobic glycolysis, proliferation, progression, and aggressiveness of NB. circ-CUX1 binds to EWSR1 to enable its contact with MAZ, leading to transactivation of MAZ and transcriptional modification of CUX1 and other genes linked with cancer progression." (PMID 33718173, 2021). "However, a pile of data show that both SAF/MAZ and Elk-1 play central role in inflammation and cancer pathogenesis." (PMID 30610159, 2019). "As inhibition of SAF-1 can suppress Ras and VEGF expression, these findings offer a new possibility for cancer therapy by targeting SAF-1/MAZ function that may provide an improved treatment option for cancer." (PMID 25449683, 2015). "Studies have reported that MAZ may act as an oncogene to promote cancer progression." (PMID 34183010, 2021). "Based on the transcriptomic data of TCGA pan-cancer cohorts, the expression of RRP1B, RRP1, MAZ, DUS1L, and HGH1 was identified to correlate positively with the expression of SLC19A1 in 40 types of cancers." (PMID 40149548, 2025). "Previous studies have shown that MAZ activates the expression of a variety of genes, including c-Myc, insulin, VEGF, and the RAS gene family in cancer cells." (PMID 35456450, 2022). "These motifs were similar to motifs of the TFs MAZ, the CAC-binding protein, and SP1, which were discovered in at least three of the five cancer types." (PMID 28684851, 2017). "For instance, motifs of the TFs SP1, MAZ, and the CAC-binding protein were shared by GSs from at least three of the five cancer types." (PMID 28684851, 2017). "The evidences that overexpression of SAF-1/MAZ occurs in many human cancers and SAF-1/MAZ transcription factor is a target of activated Ras proteins, raised the questions, what downstream pathways are affected during aberrant activation of SAF-1 in cancer." (PMID 25449683, 2015). "The functional contribution of MAZ splice isoforms in cancer has not been investigated." (PMID 40411278, 2025). "Similarly, MAZ, a C2H2-type zinc finger protein, orchestrates the transcription of various genes, including matrix metalloproteinases and serum amyloid A, playing crucial roles in metabolic diseases, cancers, and other pathological conditions." (PMID 38255847, 2024).
genetic disease (1 paper, 2023). "Among protein-coding genes located between BP4 and 5, five genes, including TAOK2 (a pLI score of 1.00), CORO1A (0.97), MAZ (0.93), PAGR1 (0.74), and PRRT2 (0.59), have a pLI value of 0.5 or more and are associated with symptoms related to 16p11.2 deficits and are implicated in genetic disease." (PMID 38203422, 2023).
infection (1 paper, 2012). The state of being infected such as from the introduction of a foreign agent such as serum, vaccine, antigenic substance or organism. "The cell cycle is further impacted by MAZ’s interaction with MYC, which we suspect is involved in cell cycle arrest, since many of MYC’s target proteins were downregulated during infection." (PMID 22937776, 2012).
MAZ also shares sentences with these, for which no sentence is quoted: colon cancer (4 papers); triple-negative breast carcinoma (4); cervical cancer (2); lung carcinoma (2); acute myeloid leukaemia (1); astrocytoma (1); Blindness (1); breast tumors (1); colorectal adenocarcinoma (1); congenital cataracts (1); endometriosis (1); hematopoietic cancer (1); Hypertension (1); Marfan syndrome (1); mastitis (1); metabolic disease (1); metastasis (1); metastatic tumors (1); microphthalmia (1); neutropenia (1); optic nerve hypoplasia (1); pancreatic ductal adenocarcinoma (1); papillary thyroid carcinoma (1); Parkinson disease (1); prostate adenocarcinoma (1); renal carcinoma (1); renal cell carcinoma (1); retinitis pigmentosa (1); ST Elevation Myocardial Infarction (1); stomach adenocarcinoma (1).